SYNJ2BP-COX16 (SYNJ2BP-COX16 readthrough)
Gene: Protein-coding gene on chromosome 14 (70,326,064 to 70,417,074, reverse strand). Ensembl gene ENSG00000258644.
Genetic constraint (gnomAD): Loss-of-function variants: 18 observed, 22.62 expected, observed/expected ratio (o/e) 0.8, 90% interval 0.55 to 1.18. The upper end of that interval is the gene's LOEUF score, 1.18, which puts it in group 5 of 6, group 1 being the genes least tolerant of losing a copy. Missense variants: 205 observed, 215.19 expected, observed/expected ratio (o/e) 0.95, 90% interval 0.85 to 1.07. Synonymous variants: 72 observed, 78.31 expected, observed/expected ratio (o/e) 0.92, 90% interval 0.76 to 1.12.